KIF6 (kinesin family member 6)
Synonyms: C6orf102; dJ1043E3.1; MGC33317; dJ137F1.4; dJ188D3.1; DKFZp451I2418
Tractability: No criterion of Open Targets' tractability assessment is met for any kind of drug.
Target class: Other cytosolic protein
Gene: Protein-coding gene on chromosome 6 (39,329,990 to 39,725,408, reverse strand). Ensembl gene ENSG00000164627.
Subcellular location: Cytoplasm, cytoskeleton
Subcellular location (Human Protein Atlas): Basal body; Centrosome; Cytosol; Nucleoplasm
Pathways (Reactome):
Hemostasis: Kinesins
Vesicle-mediated transport: COPI-dependent Golgi-to-ER retrograde traffic
Gene Ontology:
Molecular function: protein binding; ATP binding; microtubule binding; microtubule motor activity
Biological process: microtubule-based movement
Cellular component: kinesin complex; cytoskeleton
Genetic constraint (gnomAD): Loss-of-function variants: 54 observed, 59.85 expected, observed/expected ratio (o/e) 0.9, 90% interval 0.72 to 1.13. The upper end of that interval is the gene's LOEUF score, 1.13, which puts it in group 4 of 6, group 1 being the genes least tolerant of losing a copy. Missense variants: 538 observed, 602.87 expected, observed/expected ratio (o/e) 0.89, 90% interval 0.83 to 0.96. Synonymous variants: 222 observed, 227.95 expected, observed/expected ratio (o/e) 0.97, 90% interval 0.87 to 1.09.
Homologues: Orthologues: chimpanzee KIF6 (99% identical), macaque KIF6 (95% identical), dog KIF6 (85% identical), rabbit KIF6 (84% identical), rat Kif6 (83% identical), mouse Kif6 (82% identical), guinea pig KIF6 (77% identical), tropical clawed frog kif6 (63% identical), zebrafish kif6 (54% identical). Paralogues in human: KIF9 (29% identical), KIF15 (27% identical), KIF5A (23% identical), KIF5C (22% identical), CENPE (22% identical), KIF11 (22% identical), KIF5B (22% identical), KIF16B (21% identical), KIF4B (21% identical), KIF4A (21% identical), KIF7 (21% identical), KIF3A (21% identical), and 29 more.
Diseases named in the same sentence as KIF6 in open-access papers:
KIF6 is named in the same sentence as 37 diseases in open-access papers, as found by Europe PMC text mining. Sharing a sentence is not in itself a finding about the gene and the disease. The quoted sentences say what the papers report.
coronary heart disease (15 papers, 2010 to 2023). "KIF6: The KIF6 719Arg variant in the Kinesin Family Member 6 gene is linked to an elevated risk of coronary heart disease." (PMID 37965396, 2023). "This particular KIF6 variant has been shown to respond more effectively to statin therapy for the prevention of coronary heart disease." (PMID 37965396, 2023). "Next to this, to the best of our knowledge, this represents the first study implicating KIF6 variants with obesity in men only, and point to the possible involvement of this genetic locus in the known gender-related differences in coronary artery disease risk." (PMID 29295555, 2017). "Kinesin-like family 6 (KIF6) is potentially both a prognostic marker of coronary heart disease risk and a predictive marker of statin efficacy." (PMID 25562358, 2012). "A polymorphism in KIF6 has been associated both with risk of coronary heart disease and response to statin treatment." (PMID 25562358, 2012). "A single nucleotide polymorphism (SNP) in the gene for the KIF6 protein—a member of the kinesin 9 family—has been reported to be associated with coronary heart disease (CHD) and event reduction during statin therapy." (PMID 20927332, 2010). "The Ottawa Heart Genomics case-control study investigated the association between KIF6 719Arg and MI in a population with angiographically defined coronary artery disease." (PMID 20927332, 2010). "Moreover, this represents the first study implicating KIF6 variants with obesity in men, and point to the possible involvement of this genetic locus in the known gender-related differences in coronary artery disease." (PMID 29295555, 2017). "There has been considerable debate within the cardiovascular community regarding the role of kinesin-like protein 6 (Kif6) in coronary artery disease." (PMID 23355886, 2013). "KIF6 is not directly involved in lipid metabolism; however, several studies reported the association between KIF6 gene polymorphisms, coronary heart disease and events reduction from statin therapy." (PMID 29295555, 2017). "Hitherto, all studies have focused on investigating polymorphism in the KIF6 gene within the context of coronary artery disease yet to our knowledge there has been no investigation (experimental or clinical) into its function (if any) on heart function." (PMID 23355886, 2013). "Interestingly, KIF6 has previously been proposed as locus for susceptibility to coronary heart disease, while other studies did not substantiate this association." (PMID 30475797, 2018). "Furthermore, some (but not all) KIF6 719Arg carriers undergoing statin therapy have shown a greater reduction of coronary heart disease compared to non-carriers." (PMID 29295555, 2017).
myocardial infarction (9 papers, 2010 to 2023). Gross necrosis of the myocardium, as a result of interruption of the blood supply to the area, as in coronary thrombosis. "Extensive investigations over a decade (including large-scale prospective studies) identified a close association between one specific KIF6 variant (KIF6 719Arg) and the incidence of myocardial infarction." (PMID 36833179, 2023). "A KIF6 variant in man has been reported to be associated with adverse cardiovascular outcomes after myocardial infarction." (PMID 23355886, 2013). "There is a 50% greater risk for recurrent myocardial infarction in carriers of the KIF6 719Arg variant, which suggests poorer survival for this genotype." (PMID 21435211, 2011). "The CHS 13-year follow-up of 3,849 white men and women aged 65 years and older showed that KIF6 719Arg increased the risk of incident myocardial infarction by 29%." (PMID 21435211, 2011). "Disproportionate CHD survival for KIF6 Trip719Arg carriers is suggested by their 50% greater risk for recurrent myocardial infarction." (PMID 21435211, 2011). "Additionally, in extensive population studies, it was found that KIF6 variants were associated with salutary reduction in myocardial infarction and fatal coronary events with statin therapy." (PMID 36833179, 2023). "Previously, we verified that the common KIF6 polymorphism Trp719Arg is involved in lipid metabolism and CHD, reporting that it was associated with significantly higher TG levels with increased myocardial infarction risk in angiographic CHD patients." (PMID 25629058, 2014). "We investigated whether this KIF6 variant was associated with non-fatal myocardial infarction (MI) in a case-control study of an admixed population from the Central Valley of Costa Rica." (PMID 20927332, 2010). "The potential patient populations for KIF6 p.Trp719Arg testing include CAD patients with or without a family history of CAD or myocardial infarction (MI), and patients considering statin therapy." (PMID 20975779, 2010). "That is, zero on the X-axis indicates that even though KIF6 719Arg carriers are more likely to have a myocardial infarction than is a noncarrier, given that a myocardial infarction has occurred, a KIF6 719Arg carrier is no more likely to die from the event than is a noncarrier." (PMID 21435211, 2011).
scoliosis (8 papers, 2018 to 2023). A congenital or acquired spinal deformity characterized by lateral curvature of the spine. "Mutations in ptk7 or kif6, which affect the formation of ependymal cilia, induce IS-like scoliosis in zebrafish, implicating CSF flow as a crucial regulator of spine stability." (PMID 33251213, 2020). "A transgenic zebrafish for mutated-kif6 gene developed a scoliosis phenotype identical to scoliosis mutant, confirming that spine curvature is due to the loss of KIF6 function." (PMID 31828085, 2019). "In scoliosis, the genome sequencing identified a nonsense mutation in kinesin family member 6 (kif6 (gw326)) gene." (PMID 31828085, 2019). "Furthermore, another study found, in zebrafish, that mutations in KIF6 are related to scoliosis." (PMID 36833179, 2023). "To date, multiple zebrafish genetic mutants (e.g., ptk7, POC5, kif6) have linked genes involved in cilia and ciliary motility to a progressive scoliosis, giving potential insight into molecular mechanisms that may regulate scoliosis development." (PMID 37239418, 2023). "The cytoskeletal kinesin kif6 was shown to be necessary for proper spine development in zebrafish, and mutations in kif6 also appeared in a zebrafish ENU genetic screen for scoliosis." (PMID 34208743, 2021). "Among the genes that have been confirmed to be involved in the development of scoliosis in humans (TBX6, FGF3, LBX1, POC5, TTLL1) and vertebrates (Kif6 and Ptk), several are ciliary genes." (PMID 37239471, 2023). "We previously reported that kif6 mutant zebrafish are adult viable exhibiting larval-onset scoliosis without obvious heart defects." (PMID 30475797, 2018). "Interestingly, we did not observe scoliosis in the Kif6 mutant mice, despite being of an appropriate age when IS-like scoliosis can manifest in mouse." (PMID 30475797, 2018). "Although AIS in humans is defined as scoliosis without vertebral fusions, other AIS zebrafish models (col8a1a and kif6) display vertebral fusions due to differences in the spinal development between zebrafish and humans but are considered good models of AIS20,33." (PMID 30301978, 2018).
atherosclerosis (4 papers, 2011 to 2023). A disease characterized by the build-up of fatty material and calcium deposition in the arterial wall resulting in partial or complete occlusion of the arterial lumen. "Initial reports using a candidate gene based approach in several atherosclerosis population cohorts observed an increase risk of adverse coronary events in carriers of the rs20455 C variant in the KIF6 gene which leads to a Trp719Arg substitution in the Kif6 protein." (PMID 23355886, 2013). "We have briefly described in the introduction the important intracellular roles served by kinesins such as KIF6 and the early studies by Iakoubova, Schiffman, and colleagues, demonstrating that KIF6 is intimately involved with atherosclerosis and also with statin responsiveness." (PMID 36833179, 2023). "The nonsignificance of the Ottawa Heart Genomics Study may also reflect in part an effect of the KIF6 genotypes on CHD that is independent of the extent of atherosclerosis." (PMID 21435211, 2011).
Hydrocephalus (3 papers, 2018 to 2023). Hydrocephalus is an active distension of the ventricular system of the brain resulting from inadequate passage of CSF from its point of production within the cerebral ventricles to its point of absorption into the systemic circulation. "We engineered an analogous, C-terminal truncating mutation of KIF6 in mouse, which displays severe hydrocephalus and defects of EC cilia providing strong evidence for pathogenicity of the mutation in the child." (PMID 30475797, 2018). "Taken together these data suggested a cellular mechanism centered on defective ECs underlying the development of hydrocephalus in Kif6 mutant mice." (PMID 30475797, 2018). "To determine whether a more N-terminal truncated Kif6 mutation would result in a more severe hydrocephalus phenotype, we isolated a conditional-ready Kif6 allele, where exon 4 is flanked by LoxP sites (Kif6tm1c) (KOMP repository)." (PMID 30475797, 2018). "Taken together, these results suggest that the onset of hydrocephalus in Kif6 mutant mice is primarily due to a general defect of cilia formation (ciliogenesis) and not the result of defects in differentiation of the ECs or a loss of EC cilia as the result of the onset of hydrocephalus." (PMID 30475797, 2018). "These Kif6 mutant mice display severe hydrocephalus, coupled with defects in the formation of EC cilia." (PMID 30475797, 2018). "Knock-out mice for genes involved in ciliogenesis such as Cadherin EGF LAG Seven-Pass G-Type Receptor 2/3 (Ceslr2/3), Intraflagellar transport 88 (Ift88), and Kinesin family member 6 (Kif6), all presenting ependymal cell cilia dysfunction, also exhibit hydrocephalus." (PMID 36859317, 2023). "Similarly, we observed hydrocephalus and a reduction in EC cilia in kif6 mutant zebrafish." (PMID 30475797, 2018). "Together these data suggest that Kif6 mutant mice display postnatal-onset, progressive hydrocephalus, without obvious overgrowth of neural cortex." (PMID 30475797, 2018). "The milder phenotype of Kif9 mutant mice compared to Hydin KO mice, such as subfertility, no abnormalities in axonemal ultrastructures, or no overt hydrocephalus, may be due to the compensation by KIF6." (PMID 32072696, 2020). "Furthermore, while we observe a clear role for KIF6 in maintaining the ventricular system in mouse and zebrafish, the patient does not have obvious hydrocephalus." (PMID 30475797, 2018).
Obesity (3 papers, 2017 to 2025). Accumulation of substantial excess body fat. "Recent research has identified another KIF6 variant, rs9471077, which has been associated with an increased risk of obesity in males." (PMID 41009965, 2025). "In particular, KIF6 polymorphisms were associated with a lower (rs20455) or higher (rs9471077 and rs9462535) risk of obesity, in males only." (PMID 29295555, 2017). "KIF6 variants were associated with a significantly lower (rs20455) or higher (rs9471077 and rs9462535) risk of obesity, in males only." (PMID 29295555, 2017). "Interestingly, KIF6 polymorphisms (rs20455, rs9471077 and 9462535) were associated with risk of obesity, calculated as waist circumference, but in males only." (PMID 29295555, 2017). "However, the association between KIF6 polymorphisms and obesity needs confirmation or refutation in additional studies." (PMID 29295555, 2017). "Our results showed that KIF6 variants might confer risk of obesity in men only." (PMID 29295555, 2017). "Recently, GWAS studies have identified several loci associated with obesity, mostly defined according to BMI values; however, none of them reported any association with KIF6 variants." (PMID 29295555, 2017).
Cognitive impairment (2 papers, 2013 to 2018). Abnormal cognition is characterized by deficits in thinking, reasoning, or remembering. "Here we suggest that KIF6 has a uniquely specific function in the EC cilia in vertebrates, resulting in both cognitive impairment and macrocephaly in a child with a homozygous one-base pair deletion." (PMID 30475797, 2018).
diabetes (2 papers, 2014 to 2025). "In the multivariate logistic regression analysis, the following variables were included: SLC30A8 (CC), PSRC1 (AA + GA), KIF6 (CC), diabetes, age, smoking, hypertension, dyslipidaemia, BMI, and physical inactivity." (PMID 41009965, 2025).
Hypertension (2 papers, 2021 to 2025). The presence of chronic increased pressure in the systemic arterial system. "The results of the FPRP analysis confirmed the noteworthy associations of KIF6 rs20456 and rs6930913 polymorphism and hypertension susceptibility at the prior probability level of 0.25 (FPRP < 0.200)." (PMID 34961832, 2021). "In this study, two tag SNPs (rs20456 (c.2180 + 130T > C) and rs6930913 (c.1427–798C > T)) of KIF6 with minor allele frequency ≥0.1 were selected to investigate the relationships between KIF6 and hypertension in a northeast Chinese Han cohort." (PMID 34961832, 2021). "This study aimed to investigate the relationship between kinesin-like family 6 (KIF6) polymorphisms and hypertension in a northeast Chinese cohort." (PMID 34961832, 2021). "In addition, the FPRP test suggested a truly significant relationship between KIF6 rs20456 and rs6930913 polymorphisms and hypertension susceptibility in the northern Chinese Han population." (PMID 34961832, 2021). "Previously, we carried out a SNP discovery by Affymetrix Genome-Wide Human SNP Array 6.0 with pooled genomic DNA samples from 740 hypertensive patients and 361 normal controls (unpublished data), which revealed a significant association between kinesin-like family 6 (KIF6) and hypertension." (PMID 34961832, 2021). "This study's gene-environmental analysis showed that the associations between SNPs (rs20456 and rs6930913) in KIF6 and hypertension could be partly modified by smoking." (PMID 34961832, 2021). "In this study, two single nucleotide polymorphisms of KIF6 (rs20456 and rs6930913) and their haplotype were analyzed in 382 hypertension patients and 378 controls with SHEsis analysis platform, and the gene-environmental interactions were evaluated with logistic regression analysis." (PMID 34961832, 2021). "In conclusions, KIF6 might affect the susceptibility of hypertension." (PMID 34961832, 2021). "The relationship between SNPs (rs20456 and rs6930913) of KIF6 and hypertension was modified by smoking status under some genetic models." (PMID 34961832, 2021). "In all, additional investigations are warranted to elucidate the pathophysiological functions of KIF6 in hypertension." (PMID 34961832, 2021). "The present study has identified a close relationship between KIF6 SNPs (rs6930913 and rs20456) and hypertension, modified by smoking status." (PMID 34961832, 2021). "This study explored significant relationships of two SNPs (rs20456 and rs6930913) in KIF6 with hypertension in a northeast Chinese Han cohort." (PMID 34961832, 2021). "First, more SNPs or other genetic marks should be analyzed to ensure the relationship between KIF6 and hypertension." (PMID 34961832, 2021). "As far as we know, this is the first report on the relationship between KIF6 and hypertension." (PMID 34961832, 2021). "This study investigated close relationship between KIF6 and hypertension after adjusting for demographic characteristics, which might provide one genetic mechanism for hypertension." (PMID 34961832, 2021). "However, it remains unknown whether KIF6 is associated with hypertension or not." (PMID 34961832, 2021).
Alzheimer disease (1 paper, 2013). A progressive, neurodegenerative disease characterized by loss of function and death of nerve cells in several areas of the brain leading to loss of cognitive function such as memory and language. "Recent research has demonstrated associations between statin use, KIF6 719Arg carrier status, and cholesterol levels and amnestic mild cognitive impairment (aMCI) and Alzheimer's disease (AD) patients." (PMID 24455405, 2013).
aneurysm (1 paper, 2023). Bulging or ballooning in an area of an artery secondary to arterial wall weakening. "Methods: 1108 subjects (899 aneurysm and 209 dissection patients) had KIF6 719Arg variant status determined." (PMID 36833179, 2023). "We see many aneurysm genes represented in both KIF6 variant carriers and non-carriers (at various levels of pathogenetic likelihood)." (PMID 36833179, 2023).
aortic aneurysm disease (1 paper, 2023). "Thus, there appears to be fundamental biological evidence supporting a possible role of the kinesin family, and KIF6 in particular, in promoting aortic aneurysm disease." (PMID 36833179, 2023).